PWP2 (PWP2 small subunit processome component)
Description:
Part of the small subunit (SSU) processome, first precursor of the small eukaryotic ribosomal subunit. During the assembly of the SSU processome in the nucleolus, many ribosome biogenesis factors, an RNA chaperone and ribosomal proteins associate with the nascent pre-rRNA and work in concert to generate RNA folding, modifications, rearrangements and cleavage as well as targeted degradation of pre-ribosomal RNA by the RNA exosome.
Synonyms: PWP2H; EHOC-17; UTP1
Tractability: Small molecule: a structure with a bound ligand is known. PROTAC: ubiquitination databases record sites on it; its protein half-life has been measured.
Gene: Protein-coding gene on chromosome 21 (44,107,358 to 44,131,181, forward strand). Ensembl gene ENSG00000241945.
Subcellular location: Nucleus, nucleolus
Subcellular location (Human Protein Atlas): Nucleoli; Cytosol
Pathways (Reactome):
Metabolism of RNA: Major pathway of rRNA processing in the nucleolus and cytosol; rRNA modification in the nucleus and cytosol
Gene Ontology:
Molecular function: protein binding; RNA binding
Biological process: ribosomal small subunit biogenesis; maturation of SSU-rRNA; maturation of SSU-rRNA from tricistronic rRNA transcript (SSU-rRNA, 5.8S rRNA, LSU-rRNA); ribosomal small subunit assembly
Cellular component: nucleolus; small-subunit processome; nucleoplasm; Pwp2p-containing subcomplex of 90S preribosome
Homologues: Orthologues: chimpanzee PWP2 (99% identical), macaque PWP2 (99% identical), mouse Pwp2 (89% identical), rat Pwp2 (89% identical), guinea pig PWP2 (89% identical), pig PWP2 (87% identical), dog PWP2 (86% identical), tropical clawed frog pwp2 (68% identical), zebrafish pwp2h (67% identical), Drosophila melanogaster CG12325 (47% identical), Caenorhabditis elegans F55F8.3 (38% identical).
Diseases named in the same sentence as PWP2 in open-access papers:
PWP2 is named in the same sentence as 11 diseases in open-access papers, as found by Europe PMC text mining. Sharing a sentence is not in itself a finding about the gene and the disease. The quoted sentences say what the papers report.
gastric adenocarcinoma (2 papers, 2021 to 2022). "PWP2 promoted invasion and migration of Gastric Adenocarcinoma." (PMID 36685828, 2022).
folate deficiency (1 paper, 2017). A nutritional condition produced by a deficiency of FOLIC ACID in the diet. "In addition, another outcome in our study that interested us was that, even in folate deficiency, the promoter CpG islands of some genes, such as CXADR, PWP2 and PTTG1IP, still presented a state of hypermethylation." (PMID 28881655, 2017).
tumor (4 papers, 2021 to 2022). "Among the 10 survival-related genes included in the signature, the risk-associated genes PWP2 and TGFB1 have been suggested to be associated with GC invasion and metastasis, and ZBTB7A, a protection-associated gene, plays a tumor-suppressive role in GC cells." (PMID 34413861, 2021). "Six genes overlapped in the three top 50 lists for tumor response, overall clinical response, and PFS, including MAGOH, C16orf87, ORC1, NAA35, PWP2, and SIAH2." (PMID 35892846, 2022). "According to the expression levels and regression coefficients, the downregulated BAX, PWP2, SERTAD1, S1PR4, ZFAND1, NUDT13 and ZNF107 with HR < 1 were considered as tumor suppressors, whereas the MVD, BAD, CPNE7, CPNE7, UTP23 and ZNF124 upregulated with HR > 1 were regarded as oncogenes." (PMID 36685828, 2022).
cancer (2 papers, 2020 to 2025). A tumor composed of atypical neoplastic, often pleomorphic cells that invade other tissues. "DISP2 encodes a protein related to proteasome-mediated degradation and signalling by Hedgehog leads to pathological consequences in cancers, and PWP2 has been found to promote in-vitro invasion and migration of cancer cell lines." (PMID 40622919, 2025).
PWP2 also shares sentences with these, for which no sentence is quoted: cortical atrophy (1 paper); developmental delay (1); lung adenocarcinoma (1); melanoma (1); microcephaly (1); neurodevelopmental disorder (1); Primary microcephaly (1).